TNF (tumor necrosis factor)
Diseases named in the same sentence as TNF in open-access papers (continued):
Sharing a sentence is not in itself a finding about the gene and the disease.
viral infection (1,241 papers, 2005 to 2026). "The interaction between ACE-2 and SARS-CoV-2 is a vital issue in viral infections, causing the release of inflammatory proteins like TNF-α." (PMID 39854441, 2025). "Some researchers linked the hemophagocytic mechanism of non-viral infection to the excessive production of activating cytokines (such as TNF-α and interferon-γ), leading to macrophage activation." (PMID 41020231, 2025). "Understanding the mechanisms controlling TNF expression during viral infection is critical, as this cytokine has been linked to severe disease caused by major respiratory viruses such as SARS-CoV-2, influenza virus, and the pneumoviruses RSV and HMPV." (PMID 41346628, 2025). "The KEGG pathway analysis revealed significant associations with pathways such as IL-17, TNF, viral infection, AGE-RAGE, cancer, and PI3K-Akt signaling pathways." (PMID 40788315, 2025). "There was also an unexpected downregulation of genes associated with viral infection and several inflammatory pathways, including TNF, chemokine, and IL‐17 signaling, (e.g., CXCL1 and CXCL8)." (PMID 39836544, 2025). "To study the role of TNF-α in the development of pathologies associated with viral infection, we generated a Tnfa knockout mouse strain." (PMID 38256229, 2024). "Viral infection can activate extracellular pathways mediated by TNF-α and further activate Caspase-3, which causes cell apoptosis." (PMID 36851415, 2023). "The results showed that cytotoxicity was caused by cytokines secreted by HCC cells after M1 virus infection, such as tumor necrosis factor- α (TNF- α), IL-8, IL-1A." (PMID 37182136, 2023). "The results showed that luteolin upregulated the expression of IFN-γ, downregulated the expression of TNF-α and IL-4, inhibited the inflammatory response caused by a viral infection, and improved the expression of interferon." (PMID 36830548, 2023). "We showed that this reduction in unswitched memory B cells is significantly associated with elevated levels of TNFα during viral infection." (PMID 37638016, 2023). "The monotonically increasing genes (Up–Up; 85) are associated with cytokine pathways (e.g., TNF signaling), viral infection, and inflammation-based diseases." (PMID 37446105, 2023). "The presence of bacterial and viral infections causes overproduction of pro-inflammatory cytokines in the mother’s body, such as interferon, tumor necrosis factor (TNF) or interleukins." (PMID 37108086, 2023). "For LAG-3, which is directly associated with a reduced immune response to viral infections, we observed a trend toward higher expression in patients treated with anti-TNF, in contrast to patients treated with vedolizumab." (PMID 38155275, 2023). "For a particular cell cluster, cluster 1 (CD8 + Temra) was enriched in apoptosis, whereas cluster 2 (CD8 + Tem) was associated with viral infections, Toll-like receptor signalling, and TNF signalling." (PMID 36127695, 2022). "The cytokine storm resulted from the increased level of pro-inflammatory cytokines such as interleukins (IL-1, IL-6), interferon, and tumor necrosis factor (TNF-α), as immune response to virus infection, causes severe symptoms in the lung." (PMID 37521846, 2022). "Three of these were associated with immune system regulation: the TNF signaling pathway, Fc gamma R-mediated phagocytosis, and C-type lectin receptor signaling pathway; others were clustered into the nervous system, viral infection, and cancer development." (PMID 36212128, 2022). "We also detected the inflammatory cytokines including IL-6 and TNF-α which play important roles in viral infection caused tissue damage and cytokine storm after the infected cell were treated with let-7b/f mimics." (PMID 35873150, 2022). "IFN-β administration to NS mice had the strongest pro-inflammatory responses to virus infection with an increase in differential expression of genes associated with inflammation, such as IL-6, TNF-α and IL-8." (PMID 35260752, 2022).
viral infection (continued). "The specific anti-virus mechanisms of emodin involved vary from virus to virus, while the common denominator is the ability to suppress the inflammatory response caused by viral infection, such as decreasing the expression of IL-6, TNF-α and IFN-β." (PMID 35600857, 2022). "Anti-TNF agents such as infliximab have been associated with an increased risk of mycobacterial infections, invasive fungal infections, viral infections as well as bacterial pathogens." (PMID 33785062, 2021). "In viral infection, overexpression of the inflammatory cytokines like Tumor Necrosis Factor alpha (TNFα) causes initiation of the immune system response cascade that directly affects the function of cardiomyocytes and their survival." (PMID 33937353, 2021). "We previously suggested this possibility because vICA-deficient virus infection induced higher levels of TNF early during infection." (PMID 34578288, 2021). "Several members of the TNF-signaling pathway have been implicated in viral infection and TNF-receptor blockage increases susceptibility to viral infection." (PMID 33431886, 2021). "In fact, TNF-α knockout models have shown a crucial role of TNF-α in host defense in viral infections, and TNF-α inhibition is associated with poor prognosis and death in different animal models." (PMID 34439967, 2021). "Lactoferrin contained in the preparation administered directly into the throat has an antiseptic effect, stimulates the immune system and reduces necrotic TNF-alpha factors in viral infections caused by SARS-CoV-2 and in inhibiting the influenza A/WS/33 virus." (PMID 34200055, 2021). "TNF- α is a central pro-inflammatory cytokine in viral diseases, and blocking TNF- α or its receptor decreases SARS-CoV-associated disease severity and mortality in mice." (PMID 34513735, 2021). "Here, we show that exposure to TNF, which is secreted by macrophages during viral infection, causes cells to change their decision strategy from “slow and accurate” to “fast and error-prone”." (PMID 34016976, 2021). "Possible side-effects should also be considered for other compounds: the general toxicity profiles of anti-TNF alpha drugs enhancing the risk for bacterial, fungal, and virus infection." (PMID 33445810, 2021). "This is based on the fact that pro-inflammatory cytokines such as IL-6 and TNF-α are released at high levels in response to viral infection and hence predisposed the occurrence of the disorder." (PMID 33802042, 2021). "Treatment of the Supnt with both Abs further restored the susceptibility of MDMs to CCR5 HIV-1 Env-tropic virus infection, thus underlining the antiviral impact of IL-1β and TNF-α." (PMID 32994328, 2020). "E3-RIDα down-regulates an EGF receptor signaling pathway, which overrides NFκB negative feedback control in the nucleus, and is induced by cell stress associated with viral infection and exposure to the pro-inflammatory cytokine TNF-α." (PMID 31349602, 2019). "Among the children of mothers under anti-TNF-α and thiopurine combination treatment, the risk of bacterial or viral infections was amplified by a factor of 2.7 compared to those under anti-TNF-α monotherapy." (PMID 30643992, 2019). "The proinflammatory cytokine TNF-α can cause tissue injury and septic shock, which can lead to pathological conditions such as bacterial and viral infections, autoimmune conditions and inflammatory diseases." (PMID 31775224, 2019). "To further characterize the role of TNF during viral infection, we infected TNFR1- and TNFR2-deficient mice with VSV." (PMID 29142134, 2018). "TNF-α is produced upon bacterial, fungal and/or viral infections and have been shown to cause more severe inflammation in patients with CRSwNP18,19." (PMID 29367682, 2018). "TNF-α, produced upon bacterial, fungal or viral infections, is known to cause more severe inflammation in patients with CRSwNP18,19." (PMID 29367682, 2018).
viral infection (continued). "It is known that immunosuppression is a risk factor for virus-associated cancers, and TNF-inhibitor use decreases host defense against viral infections." (PMID 28717771, 2017). "The results point to the signaling route involving TLR3, MIF, and TNFα being active in TBE virus infection and contributing to the risk of an overt neuroinvasive disease." (PMID 28646884, 2017). "Taken together our data suggested subtle differences in the activity of pathways governing cell response to viral infection including TNF, EIF2, Type 1 interferon and the NFκB complex associated pathways comparing Makona with Ecran in A549 cells." (PMID 28240256, 2017). "Virus-specific T cells produce copious amounts of IFNγ and TNFα that in turn affect hematopoiesis; besides, chronic (latent or active) viral infections can induce chronic inflammation, associated with increased risk of developing BM pathology." (PMID 27695457, 2016). "A well-known example is anti-TNF therapies that are associated with reactivation of latent tuberculosis and viral infections as well as an increased risk of opportunistic infections." (PMID 27897220, 2016). "Elevated numbers of mo-DCs that express CCR2 (chemokine receptor for CCL2) or produce high amounts of TNF-α and NO are associated with greater morbidity and mortality in response to viral infection." (PMID 26965109, 2016). "The genes modulated by TNF-α were significantly enriched for those encoding proteins involved in the control of type 1 interferon signalling and the immune response to viral infection." (PMID 25781011, 2015). "TNF-α inhibited viral infections, and endogenous TNF-α inhibited the enhanced susceptibility to infectious diseases." (PMID 26694452, 2015). "It is well established that most viral infections cause damage by an interplay of direct infection and concomitant host response, evidenced by up-regulation of cytokine production, notably TNFα, IL-2, IL-6, IL-8 and other chemicals." (PMID 24628767, 2014). "An important mediator involved in both the early antiviral response and a variety of immune and autoimmune phenomena associated with viral diseases is tumor necrosis factor alpha (TNFα)." (PMID 25419735, 2014). "iNOS, COX-2, IL-6, IL-8, and TNF-α secretion by activating NF-κB pathway would cause cell injury, viral infection, inflammation, and tumourigenesis." (PMID 24683359, 2014). "Since anti-TNF agents are also associated with an increased risk of viral infections, we wished to investigate the effect of an anti-TNF-α agent, infliximab, on the UVB-induced apoptosis of keratinocytes infected by HPV38." (PMID 23533798, 2013). "Direct invasion of muscles by virus has not been consistently demonstrated, and the most likely cause is thought to be myotoxic cytokines, particularly TNF released in response to viral infection." (PMID 23476836, 2013). "Mouse TNF knock-out phenotypes include abnormal immune system physiology, increased susceptibility to viral infection, and both increased and decreased susceptibility to bacterial infection." (PMID 22432004, 2012). "Taken together, this study showed that high cerebral levels of TNF in combination with a neurotropic virus infection caused spontaneous epileptic seizures indicating a cause-and-effect-relationship." (PMID 22848506, 2012). "IL-6 together with IL-1 and TNF-α acts as an endogenous pyrogen by causing fever following viral infections." (PMID 21345237, 2011). "Enbrel is an anti-TNF-α drug, and when used in combination with methotrexate, it may enhance the immunosuppressive effects, increasing the risk of bacterial, fungal, and viral infections." (PMID 40534848, 2025). "Given the roles that TNF plays during viral infection, this deficiency may have a greater impact in vivo than in vitro, leading for ST-J1 to exhibit an attenuated phenotype in vivo, relative to NL-2." (PMID 40431669, 2025).
viral infection (continued). "For example, CD56bright NK cells produce immunoregulatory cytokines, such as IFN-γ, TNF-α, and IL-10, that may support viral clearance and reduce inflammation associated with severe viral infections." (PMID 40411624, 2025). "Furthermore, abnormal elevations in TNF-α production have been associated with poor prognosis in viral infections and adverse outcomes." (PMID 39062991, 2024). "Regarding its role in viral diseases, it was found that the rs3804099 CT and TT genotypes had a protective effect on the progression of hepatitis B and C and were associated with inhibiting IL-6 and TNF-α levels." (PMID 38703289, 2024). "However, during severe viral infections, such as those caused by Ebola or influenza, TNF-α levels can rise significantly, often exceeding 100 pg/mL." (PMID 39589620, 2024). "Lastly, the body’s response to stress after virus infection, combined with the virus itself acting as an inflammatory stimulus, can cause the instability and rupture of atherosclerotic plaques, inducing the expression of IL-8, TNF-α, and other factors." (PMID 38435118, 2024). "In the US population, it was observed that seropositive children had higher levels of IL-6 and TNFα, so more evidence is required to establish whether there is an influence of viral infection on lipid metabolism and the risk of dyslipidemia." (PMID 38932286, 2024). "In addition, it has been proven that during lung injury caused by viral infection, macrophages and epithelial cells release IL-6, which interacts with TNFα synergistic effects and exerts biological effects." (PMID 37760262, 2023). "Particular lifestyle and environmental factors including sex, age, diet, smoking status, family history, history of parasite exposure, immunological factors, and viral infections may all shape the relationship between TNF-α or IFN-γ polymorphisms and LC." (PMID 37122734, 2023). "As previously reported, TNF-α is thought to be a potent inducer of neuronal injury in several neurodegenerative diseases, such as cerebral ischemia, spinal cord injury, multiple sclerosis and viral infections including HIV-associated dementia." (PMID 35215199, 2022). "This phenomenon, although not well understood, is related to inflammatory factors, with the release of cytokines (TNF-α, interleukins 6, 13, and 18, and cytotoxic factor), greater susceptibility to viral infections with possible tissue infiltration, host genetic factors, and viral load." (PMID 36146794, 2022). "In a 2004 investigation into adverse effects associated with infliximab and etanercept, M. tuberculosis was observed to be the most frequent cause of infections, but a later study looking at non-viral infections across all TNF inhibitors found that it had dropped to third place (59% to 12.5%)." (PMID 36159650, 2022). "Regarding myeloid cell phenotype role in viral infection prognosis, a M1-like shift, correlated with secretion of cytokines like IFN-γ, TNF-α, IL-6, and IL-12, both in mucosal associated and in systemic myeloid cells, was considered determinant for worse outcomes in life-threatening viral infection." (PMID 34248984, 2021). "The inability to promptly defeat a viral infection can elicit a cytokine storm, in which pro-inflammatory molecules including Interleukin-1β (IL-1β), Interleukin-6 (IL-6), and Tumor necrosis factor (TNF-α) are released in pathogenic concentrations causing systemic hyperinflammation." (PMID 33679437, 2021). "However, the expression of TNF-α and IL-6 in Arid1a-deficient BMDMs was comparable with that in control BMDMs upon virus infection." (PMID 34315861, 2021). "Overproduction of TNF-alpha, IL-1, IL-6 and IL-10 hallmark of viral infection.Investigated inflammatory profiles of patients infected with SARS in Hong Kong hospital.Use of corticosteroids significantly reduced IL-8, MCP-1 and IP-10 concentrations from 5-8 days after treatment." (PMID 32256705, 2020).
viral infection (continued). "However, inflammatory mediators released during viral infection, such as TNFα and lipopolysaccharide (LPS), can cause degradation of the glycocalyx, thus regulating the permeability of endothelium." (PMID 32825182, 2020). "Since virus infection induced elevated expression level of inflammatory factors such as IL-6 and TNF-α have been reported to be associated with severity of the disease, we next examined the anti-inflamatory effect of Emetine in the M1-polarized THP-1 macrophages." (PMID 34765997, 2020). "Upon exposure to bacterial or viral infection, osteoblasts can directly respond to pathogen-associated molecular patterns (PAMPs), such as LPS, with the release of several cytokines, including IL-1β, IL-6, and TNF-α." (PMID 31892163, 2019). "Since the proinflammatory response of DCs might contribute to antiviral immunity against LACV, we performed cytokine ELISA for hallmark cytokines of proinflammatory responses, namely, TNF-α and IL-6 after 8h and 24h of virus infection." (PMID 30917612, 2019). "The infection caused high amounts of IFN-β and TNF, possibly limiting prolonged virus infection." (PMID 30746342, 2019). "IRF5 knockout mice were reported to be susceptible to viral infections, while, the expression levels of type I IFNs and other pro-inflammatory cytokines including tumour-necrosis factor (TNF)-α, interleukin (IL)-6 and IL-12, were reduced in response to viral infections." (PMID 27350041, 2016). "Bacterial and viral infections can cause many signaling molecules, macrophages, monocytes, and neutrophils to produce inflammatory mediators such as nitric oxide, prostaglandin, and tumor necrosis factor (TNF-α)." (PMID 26800679, 2016). "LC, which is related to lymphocyte and macrophage dysfunction and decreased production of proinflammatory cytokines, such as interferon-γ and tumor necrosis factor-α, may be linked to an increased virus infection risk." (PMID 24699628, 2014). "We then directly determined if viral infection of HSAECs caused up regulation of endogenous TNFα." (PMID 21655261, 2011). "These viral infections not only cause direct damage to myocardial cells but also activate the coagulation system through cytokine storms, particularly involving interleukin-6 (IL-6) and tumor necrosis factor-alpha (TNF-α), which can lead to a hypercoagulable state." (PMID 40910144, 2025). "Moreover, bacterial lipopolysaccharide, pro-inflammatory cytokines such as TNF-α and IL-1, and viral infections may all activate NFκB, and extensive mutational analyses have revealed the NFκB binding region as being critical for IL-6 gene activation." (PMID 36771194, 2023). "Inhibition of JAK signaling may impair the immune system’s ability to produce antiviral cytokines such as interferons and tumor necrosis factor α, which may be a contributing factor to the increased risk of viral infections and reactivation of latent viral infections such as herpes zoster." (PMID 37614317, 2023). "Viral infection will cause excessive activation of immune cells, such as macrophages and neutrophils, migrating into the lung tissue and producing large amounts of inflammatory factors, such as tumor necrosis factor-alpha (TNF-α), interleukin (IL)-1, and IL-6, which is known as cytokine storm." (PMID 35784698, 2022). "Neopterin may therefore serve both as a biomarker of an early inflammatory state based on IFN-γ signaling, which should be associated with a large quantity of surface bound TNF-α ready for secretion upon an acute event, such as viral infection and ADAM17 induction." (PMID 34497777, 2021). "TNF, a famous and perhaps the most intensely studied proinflammatory cytokine, is considered to play a prominent role in the cytokine storm and has been identified as a central cytokine in acute viral diseases, including those caused by the influenza virus, dengue virus, and Ebola virus." (PMID 33224256, 2020).